PCSK9 (proprotein convertase subtilisin/kexin type 9)
Diseases named in the same sentence as PCSK9 in open-access papers (continued):
Sharing a sentence is not in itself a finding about the gene and the disease.
tumor (continued). "Corresponding to the effects of cholesterol on tumor growth, PCSK9 inhibition also has cholesterol depletion-mediated antitumor effects by regulating tumorigenic signaling pathways, ferroptosis and the TME." (PMID 39324018, 2024). "As a result, the use of PCSK9 inhibitors can systematically induce a peripheral immune response against tumor cells via optimizing their recognition by T lymphocytes." (PMID 38473748, 2024). "Several studies have shown that PCSK9 can serve as an independent prognostic factor for multiple tumors and that high expression of PCSK9 can promote tumor progression through various mechanisms." (PMID 38600469, 2024). "Firstly, we examined the genetic-level relationship between PCSK9 inhibitors and tumor development, effectively mitigating the impact of confounding variables." (PMID 38275613, 2024). "Consistent with RNA-seq analysis, Tnfrsf9 was downregulated in both D374Y and PCSK9 tumors but showed increased expression in Q152H tumor." (PMID 36588164, 2023). "To confirm PCSK9 expression in NB, we measured mRNA and protein levels of PCSK9 in paired NB and adjacent non-tumor tissues using qRT-PCR (n = 18) and western blotting (n = 18)." (PMID 37860186, 2023). "Apart from its impact on LDL-C levels, PCSK9 inhibitor also exhibits potential pleiotropic effects such as enhancing tumor response to immune checkpoint therapy, inhibiting platelet activation and thrombosis, and reducing apoptosis." (PMID 38027179, 2023). "In support of this notion, the content of biologically active unesterified cholesterol, stained by filipin was also elevated in B16 PCSK9 tumor, and further increased in D374Y and reduced in Q152H tumors." (PMID 36588164, 2023). "The inhibition of PCSK9 increases the expression of MHC I on the tumor cell surface, promoting intratumoral infiltration of cytotoxic lymphocytes." (PMID 36900189, 2023). "Knocking down or blocking PCSK9 activity through treatment with a specific antibody enhanced the effect of tumor immunotherapy in mice." (PMID 37653037, 2023). "Next, multiplexed IHC was used to explore the density and spatial distribution of CD8+ T cells with tumor cells in NSCLC tissues with different PCSK9 expression levels." (PMID 37025995, 2023). "We report here a major role of tumor-derived PCSK9 in facilitating the growth of B16 cell-generated allografts in comparison to host-derived PCSK9." (PMID 36588164, 2023). "The analysis of average tumor weight showed that reducing PCSK9 expression significantly impaired the tumor formation ability of Huh7 and PLC/PRF/5 cells in nude mice." (PMID 37151886, 2023). "First, we conducted extensive data searches from TIMER to investigate the levels of PCSK9 expression in diverse tumor types." (PMID 37860186, 2023). "A recent study showed that inhibiting PCSK9 enhanced the antigen presentation efficacy of PD-1 and influenced the tumor response to immune checkpoint treatment, although through a mechanism unrelated to its role in controlling cholesterol." (PMID 37860186, 2023). "Recently, PCSK9 was found to promote tumor progression by regulating apoptosis, metastasis, and tumor immunity via lysosomal degradation of MHC Class I molecules 26,29,50,51." (PMID 37151886, 2023). "A recent study showed that PCSK9 inhibition increased the expression of MHC protein class I proteins on the tumor cell surface." (PMID 37290532, 2023). "Previous studies have reported that the PCSK9 expression level is correlated with the proliferation of hepatocytes and the metastasis of tumor cells." (PMID 36655117, 2023). "Gradually, PCSK9 has become the target of combined chemotherapy or immunotherapy and other anti-tumor therapies." (PMID 37896137, 2023).
tumor (continued). "Further study is of great significance to fully understand the specific mechanisms of the interaction between EVs and miRNAs to regulate the expression of PCSK9 and its influence on tumor mechanisms." (PMID 37860186, 2023). "The combination of the PCSK9 inhibitor with the anti-CD137 agonist led to greater tumor volume control at 21 days after inoculation from day 5 (baseline prior to antibody injection) compared with the two single groups." (PMID 37025995, 2023). "In our work, we investigated PCSK9 expression by immunohistochemistry in tumor tissue from advanced NSCLC patients before receiving anti-PD-1 immunotherapy." (PMID 37025995, 2023). "In consensus with previous reports, tumor growth delay was observed with the PCSK9 inhibitor evolocumab and the anti-CD137 agonist 1D8 alone." (PMID 37025995, 2023). "Together, these results suggested that high PCSK9 expression in baseline tumor tissue was a deleterious factor for the efficacy of anti-PD-1 immunotherapy in advanced NSCLC patients." (PMID 37025995, 2023). "Our findings revealed that PCSK9 expression in tumor tissues was significantly higher at both the transcriptional and protein levels than in adjacent normal tissues (p < 0.001)." (PMID 37860186, 2023). "We also examined the efficacy of Pcsk9 inhibitor alirocumab in the orthotopic model and found that alirocumab resulted in significant tumor growth inhibition." (PMID 37898598, 2023). "A typical example in tumors involves the immunomodulatory function of PCSK9, which is related to cholesterol endocytosis into tumor cells." (PMID 37653037, 2023). "We also investigated the relationship between PCSK9 expression and immunological checkpoints and six tumor-infiltrating immune cells in 33 TME." (PMID 37860186, 2023). "Treating of PDAC cells with recombinant protein or neutralizing antibody revealed that Pcsk9, but not PGRN, increased PDAC proliferation under glucose-limiting conditions, indicating the role of Pcsk9 in regulating tumor growth." (PMID 37898598, 2023). "In BRCA, PCSK9 expression was involved in tumor inflammation signature, reactive oxygen species and transforming growth factor beta (TGF-β)." (PMID 37860186, 2023). "To further assess the tumor-forming ability of PCSK9, we established a liver transplantation model by orthotopically injecting Huh7 and PLC/PRF/5 cells transfected with shPCSK9#1 or a negative control (shNC) into the left hepatic lobe." (PMID 37151886, 2023). "In these studies, PCSK9 amounts correlated with increased tumor size as PCSK9 overexpression increased, while PCSK9 depletion decreased tumor size." (PMID 35162992, 2022). "Using xenograft experiments in CAM model, we further demonstrated the effect of anti-PCSK9 treatment in reducing tumor aggressiveness." (PMID 36612001, 2022). "More specifically, a very recent study reported the high expression of PCSK9 in tumor tissues in HCC patients." (PMID 36611859, 2022). "PCSK9 inhibited apoptosis of tumor cells via bax/bcl-2/caspase-9/caspase-3, which consequently stimulated the proliferation of neoplastic tissue." (PMID 35323699, 2022). "Inhibiting PCSK9 by small molecular compounds or monoclonal antibodies increases the expression of MHC I on the tumor cell surface, promoting intratumoral infiltration of cytotoxic lymphocytes." (PMID 36003387, 2022). "Taken together, current data suggest that PCSK9 levels are reduced in HCC tissues and the association of tumor PCSK9 expression with prognosis needs evaluation in future studies." (PMID 35162992, 2022). "This interesting study has brought PS, a fungal metabolite, to the spotlight as a novel small molecule that targets PCSK9 and prevents tumor growth in vitro and in vivo." (PMID 36552895, 2022). "Apart from its role in lipid homeostasis, PCSK9 is involved in various signaling pathways including antiviral activity, apoptosis and more recently, anti-tumor immune responses." (PMID 36611859, 2022).
tumor (continued). "Further exploration in the tumor microenvironment confirmed the enrichment of CD8+ T cells, CD4+ T cells and natural killer cells in PCSK9‐deficient tumors." (PMID 34962050, 2022). "Together with VLDLR and LRP1, LRP8 is also involved in tumor cell growth through its binding to the glycoprotein Proprotein convertase subtilisin/kexin type 9 (PCSK9)." (PMID 36012187, 2022). "Deletion of the PCSK9 gene in tumor cells enhances the effectiveness of immunotherapy against PD-1 and prevents the growth in tumor size." (PMID 36080373, 2022). "Autocrine PCSK9 promotes the degradation of MHC-I in tumor cells to reduce tumor-infiltrating T cell efficiency." (PMID 39872079, 2022). "The role played by PCSK9 in inflammation has been extensively studied, especially in macrophages infiltrating TME, which are referred to as tumor-associated macrophages (TAMs)." (PMID 36552895, 2022). "The genetic or pharmacological targeting of PCSK9 in tumor cells enhances CD8+ T cells’ antitumor activity as well as tumor progression." (PMID 36552895, 2022). "It has been reported that in different patient cohorts, individuals with high expression of tumor PCSK9 mRNA have a poorer overall survival rate than individuals with low expression of PCSK9 mRNA." (PMID 36230934, 2022). "Actual data tend to support a pathogenic and pro-tumoral role for PCSK9, by both maintaining cholesterol supplies and by promoting MHC-I degradation on tumor cells, favoring immune escape of tumors." (PMID 36203122, 2022). "Next, proteomic analysis, Western blot, qRT-PCR and Flow cytometry were conducted to assess downstream targets and tumor cell-derived PCSK9 action on macrophage polarization." (PMID 36242053, 2022). "For example, one study found that PCSK-9 inhibition in mice potentiated the anti-tumor effects of ICI therapy, although the direct effects of lipid metabolism have yet to be studied." (PMID 36017084, 2022). "Immunohistochemistry was used to assess the expression of PCSK9 in tumor specimens from 105 HCC patients who underwent curative resection." (PMID 33789749, 2021). "In the multivariate analysis, tumor depth and s-PCSK9-Ab level were identified as independent prognostic factors." (PMID 34504788, 2021). "They reported that while administration of the anti-PCSK9 antibodies alone delayed tumor growth of MC38 tumors, their efficacies were enhanced significantly when combined with an anti-PD1 antibody, with long-term survival of some host mice." (PMID 34504788, 2021). "TUNEL staining of formalin-fixed paraffin-embedded xenograft tumors confirmed that the apoptosis of tumor cells was inhibited after overexpression of PCSK9 and increased after downregulation of PCSK9." (PMID 33789749, 2021). "In this study, we investigated the relationship between the expression level of PCSK9 in tumor cells and patient prognosis after curative surgery, and then explored the mechanisms by which PCSK9 promotes tumor growth in HCC." (PMID 33789749, 2021). "In this study, we found that high expression of PCSK9 in HCC is related to microvascular invasion and large tumor size and is an independent risk factor for both OS and DFS in patients with HCC who underwent curative resection." (PMID 33789749, 2021). "High expression of PCSK9 in tumor tissues was related to microvascular invasion (p = 0.036) and large tumor size (p = 0.001) in HCC patients." (PMID 33789749, 2021). "Another recent study demonstrated that a nanoliposomal anti-PCSK9 vaccine limited tumor progression and improved survival in a murine model of colon carcinoma." (PMID 35097027, 2021). "In tumor-bearing mice, the transcriptional regulation of PCSK9 by glucose was found to enhance serum PCSK9 levels." (PMID 34504788, 2021).
tumor (continued). "Remarkably, tumor growth retardation and overall survival were further promoted upon treatment of syngeneic mice bearing PCSK9 knock out tumors with a mouse anti-PD1 antibody." (PMID 33677469, 2021). "In this study, we demonstrated that PCSK9 expression was lower in HCC tissues than in adjacent non-tumor samples." (PMID 33893729, 2021). "The results of in vivo experiments confirmed that PCSK9 promoted the growth of HCC and was associated with tumor cell apoptosis." (PMID 33789749, 2021). "PCSK9-neutralizing antibodies increase the expression of MHC-I proteins by promoting their recycling to the surface of tumor cells and, therefore, opposing their lysosomal degradation." (PMID 34439102, 2021). "For example, preclinical data showed that inhibition of PCSK9 (proprotein convertase subtilisin/kexin type 9) or ACAT1 (Acetyl-CoA acetyltransferase 1) can improve the anti-tumour effect of the anti-PD-1 antibody in multiple cancers." (PMID 34722305, 2021). "To determine the role of GSTP1 in the tumor-suppressive effect of PCSK9, we detected GSTP1 protein expression and JNK signaling activity." (PMID 33893729, 2021). "Subsequently, we managed to pick up HSP70 as the interacting molecule in PCSK9 tumor regulation, which played a synergistic role in the process." (PMID 33489919, 2020). "A growing number of recent studies have found that PCSK9 becomes a latent tumor-targeting molecule which has the value of potential application in a variety of tumors." (PMID 33489919, 2020). "Our in vivo experiments were also consistent with the in vitro data that PCSK9 knockdown in SGC-7901 cells significantly inhibited tumor metastasis in the lungs, as indicated by the model of xenograft nude mice." (PMID 33489919, 2020). "Knockdown of PCSK9 inhibited tumor metastasis while addition of HSP70 agonist counteracted this effect." (PMID 33489919, 2020). "This exciting finding prompted us to pursue further studies to reveal a profound understanding of PCSK9 in tumor promotion, especially in lipid metabolism." (PMID 33489919, 2020). "By contrast, PCSK9-KO and wild-type mice fed with a high cholesterol diet showed an increased number of liver metastasis, suggesting a prominent role of cholesterol in tumor-microenvironment interaction." (PMID 30254608, 2018). "Analyzing serum PCSK9 in tumor-bearing mice revealed that glucose feeding significantly upregulated its level." (PMID 30386595, 2018). "The lifetimes of many proteins range from single-digit minutes to hours (e.g. PCSK9 is on the order of 5 min, and tumor cell line-derived NIK ranges from ~5–30 min)." (PMID 30383749, 2018). "Our data demonstrate that acRoots is a novel anti-tumor agent that inhibits cholesterol metabolism though a PCSK9-mediated signaling pathway." (PMID 28178673, 2017). "We detected expression of PCSK9 in tissue samples of p-NENs and found a significantly increase than para-tumor tissues (P < 0.01)." (PMID 28036293, 2017). "Identification of PCSK9 targets should allow a better understanding of the consequences of PCSK9 inhibition for lowering LDLc and tumor metastasis." (PMID 23675525, 2013). "In this study, we conducted a comprehensive analysis of PCSK9 expression across multiple tumor types, assessing its prognostic significance using RNA sequencing data from The Cancer Genome Atlas (TCGA) and gene expression microarray data from the Gene Expression Omnibus (GEO)." (PMID 40576911, 2025). "In fact, PCSK9 was found to be abnormally highly expressed in a broad spectrum of neoplasms, indicating that PCSK9 might be a promising therapeutic target in neoplasm treatment." (PMID 40872487, 2025). "Furthermore, to assess the role of PCSK9 on DMR‐mediated tumor growth inhibition, we knocked down/out the PCSK9 in MC38 cell lines." (PMID 40125618, 2025). "The interplay between PCSK9 and cholesterol homeostasis may impact membrane dynamics and cellular migration, thereby further influencing tumor aggressiveness." (PMID 40354375, 2025).
tumor (continued). "Together with the result that methionine promotes the mRNA transcription of PCSK9 through DNA methylation, our findings proposed a possibility that tumor cell methionine metabolism contributes to epigenetic regulation and immune responses linked to tumorigenesis." (PMID 40125618, 2025). "Inclisiran, a small interfering RNA targeting PCSK9, effectively lowers LDL cholesterol and may contribute to reducing CV risk, with potential implications for tumor biology." (PMID 40364115, 2025). "Furthermore, the combination of PCSK9 inhibition and PD‐1 blockade along with 5‐fluorouracil (5‐FU) chemotherapy suppressed tumor growth in MSS CRC." (PMID 40125618, 2025). "The combination of PCSK9 inhibitors with OVA‐II tumor vaccines enhanced therapeutic efficacy." (PMID 40145543, 2025). "However, the specific mechanisms by which PCSK9 regulates tumor proliferation and invasion remain underexplored." (PMID 40328788, 2025). "However, the combination of PCSK9 inhibition with anti‐PD‐1 therapy significantly suppressed the tumor progression of MSS CRC." (PMID 40125618, 2025). "As the high expression of PCSK9 can activate HER3/EGFR to promote tumor growth and metastasis, therefore reducing PCSK9 level may be a good strategy for treating TNBC." (PMID 40192514, 2025). "PCSK9 can promote immune evasion of neoplasms and act as a promoter for several specific neoplasms." (PMID 40872487, 2025). "In hepatocellular carcinoma, PCSK9 exhibits dual roles: it can promote tumor growth by inhibiting apoptosis through the Bax/Bcl-2/Caspase pathway and also acts as a tumor suppressor by interacting with GSTP1 and inhibiting the c-Jun n-terminal kinase signaling pathway." (PMID 40764605, 2025). "And the expression of DNMT1 was strongly correlated with that of PCSK9 in tumor tissues." (PMID 40125618, 2025). "Besides, the effect of PCSK9 inhibition on tumor suppression in combination with 5‐FU treatment was also investigated." (PMID 40125618, 2025). "Considering MHC-II mediates CD4+ T-cell epitope-initiated immune responses, we hypothesized that combining PCSK9 inhibitors with long peptide vaccines may achieve synergistic anti-tumor effects." (PMID 38600469, 2024). "These pathophysiological observations provoked the hypothesis of PCSK9 being a regulator of anti-tumor responses and thus, a potential target to enhance immunity against tumors." (PMID 38672532, 2024). "Vaccines targeting PCSK9 were also investigated in tumor cells." (PMID 39736777, 2024). "Increased PCSK9 expression was related to tumor progression and poor survival." (PMID 38611089, 2024). "Both inhibitor types aim to diminish the function of PCSK9, potentially suppressing tumor growth." (PMID 38275613, 2024). "PCSK9 is a potential factor in tumor cell proliferation, invasion, and metastasis." (PMID 39282119, 2024). "Furthermore, to exclude the influence conducted by differential numbers between tumor samples and normal samples, we analyzed PCSK9 expression in paired samples of available tumor types in TCGA." (PMID 38600469, 2024). "Furthermore, we evaluated the modulation of PCSK9 on anti-tumor immunity and explored the value of targeting PCSK9 in immunotherapy." (PMID 38600469, 2024).